TFAP2C (transcription factor AP-2 gamma)
Diseases named in the same sentence as TFAP2C in open-access papers (continued):
Sharing a sentence is not in itself a finding about the gene and the disease.
colorectal cancer (7 papers, 2018 to 2024). A primary or metastatic malignant neoplasm that affects the colon or rectum. "TFAP2C facilitates the proliferation, migration, and invasion of colorectal cancer by triggering the PI3K (phosphoinositide 3-kinases) /AKT (AKT serine/threonine kinase, also known as protein kinase B, PKB) signaling pathway." (PMID 37291585, 2023). "5-FU is another anti-tumor agent; TFAP2C mediates the chemotherapy response of colorectal cancer (CRC) cells to 5-FU." (PMID 37291585, 2023). "In colorectal carcinoma, TFAP2C enhances the expression of stemness-related factors, such as Nanog homeobox (NANOG), BMI1 proto-oncogene (BMI-1), POU class 5 homeobox 1 (OCT4) and SRY-Box transcription factor (SOX2), and the phenotypes of cancer stem cells." (PMID 37291585, 2023). "As the m6A target of METTL3 found in this study, TFAP2C was found to potentiate chemoresistance, which is consistent with the findings in colorectal cancer." (PMID 32857912, 2020). "The purpose of this study is to investigate the clinical significance and biological roles of TFAP2C in colorectal cancer (CRC)." (PMID 29439714, 2018). "We further validated TFAP2C expression in our own 8 paired colorectal cancer tissues and found that mRNA and protein expression elevels of TFAP2C was differentially upregulated in CRC tissue samples compared with the matched adjacent normal tissue samples." (PMID 29439714, 2018). "Through analyzing several colorectal cancer RNA sequencing datasets from The Cancer Genome Atlas (TCGA) and ArrayExpress, we found that TFAP2C expression was dramatically elevated in CRC tissues compared with the adjacent normal colorectal tissues." (PMID 29439714, 2018). "In colorectal cancer, TFAP2C regulates stemness through various pathways." (PMID 37291585, 2023). "Additionally, both TFAP2A and TFAP2C can also bind to the P21 promoter in breast and colorectal cancer cells to enhance P21 expression." (PMID 37291585, 2023). "However, the clinical significance and biological role of TFAP2C in colorectal cancer remain largely unknown." (PMID 29439714, 2018). "TFAP2C inhibits Hippo signaling by upregulating ROCK1 and ROCK2 in colorectal cancer, thereby contributing to the stemness of colorectal cancer cells and the resistance to 5‐FU." (PMID 37799806, 2023). "There was a significant difference in the expression distribution of TFAP2C, SLC39A8, and AKR1C1 genes between the cetuximab responders and non-responders in colorectal cancer (P < 0.05)." (PMID 34249766, 2021).
prostate carcinoma (7 papers, 2019 to 2026). A carcinoma that arises from epithelial cells of the prostate gland. "In this study, the c-Myc/miR-25-3p/SLC7A11 signaling axis has been found to be mediated by the Transcription Factor AP-2γ (TFAP2C), which can decrease ferroptosis in prostate cancer and promote chemoresistance." (PMID 38994627, 2024). "Transcription factor AP-2 gamma (TFAP2C)-dependent PCAT1 suppresses ferroptosis of prostate cancer cells." (PMID 36230902, 2022). "Transcription factor AP-2 gamma (TFAP2C) transcriptionally activates lncRNA PCAT1 to suppress ferroptosis of prostate cancer cells by interacting with c-Myc." (PMID 36230902, 2022). "It has been found that SLC7A11 is involved in the development of resistance to docetaxel in prostate cancer, and the transcription factor AP-2γ (TFAP2C) inhibits ferroptosis in prostate cancer through the c-Myc/miR-25-3p/SLC7A11 signaling axis, which in turn promotes its resistance to chemotherapy." (PMID 41228362, 2025). "In prostate cancer cell lines, several AR regulators have been identified, including GATA2, HOXB13, FOXA1, and TFAP2C." (PMID 41596366, 2026).
non-small cell lung carcinoma (6 papers, 2019 to 2025). A group of at least three distinct histological types of lung cancer, including non-small cell squamous cell carcinoma, adenocarcinoma, and large cell carcinoma. "The down-regulation of tumor suppressor gene expression regulated by TFAP2C may be one of the carcinogenic causes of non-small cell lung cancer." (PMID 34732138, 2021). "ANXA9 which is related to metastasis, and the transcription factor activating enhancer-binding protein 2C (TFAP2C) that has been reported to decrease migration and invasion in pancreatic ductal adenocarcinoma and non-small cell lung cancer cells." (PMID 35872983, 2022). "For example, Chang TH al. found that miR-137 is a Slug-induced miRNA that relays the pro-metastatic effects of Slug by targeting TFAP2C in in non-small cell lung cancer (NSCLC)." (PMID 30866999, 2019). "AP-2γ inhibits GADD45B expression, with overexpressed TFAP2C suppressing GADD45B and PMAIP1 at both mRNA and protein levels in non-small cell lung cancer cells." (PMID 41373739, 2025).
germ cell tumor (5 papers, 2013 to 2022). A benign or malignant, gonadal or extragonadal neoplasm that originates from germ cells. "There, mice heterozygous for Tfap2c develop with high incidence germ cell cancer resembling human pediatric germ cell tumors." (PMID 23967156, 2013). "In testicular germ cell tumors, METTL3 promotes the m6A-modified transcription factor-activating enhancer-binding protein 2C (TFAP2C) mRNA to regulate cisplatin treatment." (PMID 34001850, 2021). "In line with this, we demonstrate that haploinsufficiency of Tfap2c or its target gene Nanos3 lead to high rate of GCC in 129S2/Sv mice, resembling human pediatric germ cell tumors." (PMID 23967156, 2013). "Moreover, we confirmed that LTR5_Hs were preferentially bound by KLF4, NANOG, POU5F1, and TFAP2C in naïve ESCs, by TFAP2C in PGCLCs, and by SOX17 in a germ cell tumor cell line using publicly available ChIP-Seq datasets." (PMID 35551519, 2022).
glioma (4 papers, 2016 to 2025). A benign or malignant brain and spinal cord tumor that arises from glial cells (astrocytes, oligodendrocytes, ependymal cells). "Specially, the present study used real-time PCR to verify the expression of key genes GRM2, GRM7, HTR2A and TFAP2C through human glioma cell line U251." (PMID 30124166, 2018). "TFAP2C was upregulated in human glioma cell line U251, being inconsistent with the prediction result, which needed to be further investigated." (PMID 30124166, 2018). "However, result of PCR analysis showed that TFAP2C was upregulated in human glioma cell line U251, which was inconsistent with the prediction result." (PMID 30124166, 2018). "The correlation between Haemophilus and TFAP2C in GBM gains context from evidence linking Haemophilus to IDH1 status and glioma grade." (PMID 41373739, 2025). "Some studies have revealed that miR-10b promotes metastasis of glioma cells through regulation of HOXD10, Bim, TFAP2C, P16, and P21." (PMID 27756250, 2016). "To further explore the specific molecular mechanism of this phenomenon, we assessed four transcription factors of Galectin-9 (AR, CEBPA, CEBPB, and TFAP2C) and found that CEBPA on chromosome 19q played a leading role in the transcriptional regulation of Galectin-9 in gliomas." (PMID 34956239, 2021).
lung adenocarcinoma (4 papers, 2019 to 2024). A carcinoma that arises from the lung and is characterized by the presence of malignant glandular epithelial cells. "MiR-10a increases cisplatin resistance in lung adenocarcinoma circulating tumor cells by targeting the PI3K/Akt pathway and also targets TFAP2C to promote Gem resistance in PDAC." (PMID 38919953, 2024). "Besides, Chen and colleagues found that TFAP2C could activate the expression of MALAT1 and thus modulate the chemoresistance of DTX-resistant lung adenocarcinoma cells." (PMID 35402284, 2022). "Of note, the Transcription Factor (TF) TFAP2C was identified among the top regulons based on the AUCell score in chemoresistant cells and not present in chemosensitive cells and has previously been implicated in EMT signalling and chemoresistance in lung adenocarcinoma, but not yet in TNBC30,31." (PMID 38472332, 2024).
invasive breast carcinoma (3 papers, 2014 to 2023). A carcinoma that infiltrates the breast parenchyma. "The downregulation in TFAP2C was observed in breast-invasive carcinoma (BRCA), KIRC, and KIRP, compared to normal cells." (PMID 36831334, 2023). "This is the case of TFAP2C, whose overexpression highlights the key role in invasive breast cancer correlating with a poorer response to anti-hormone therapy and reduced patient survival." (PMID 24586334, 2014).
Ovarian tumor (3 papers, 2013 to 2025). "Notably, nuclear expression of TFAP2C has been associated with ovarian tumor aggressiveness." (PMID 34215221, 2021). "TFAP2C is also over-expressed in primary ovarian tumors, with increased expression reported in higher stage tumors." (PMID 24023917, 2013).
pancreatic ductal adenocarcinoma (3 papers, 2018 to 2022). An infiltrating adenocarcinoma that arises from the epithelial cells of the pancreas. "miR-10a-5p promoted pancreatic ductal adenocarcinoma cells migration and invasion and enhances gemcitabine resistance by directly targeting TFAP2C." (PMID 33014878, 2020).
carcinoma in situ (2 papers, 2013). "Primary testicular tumors also overexpress TFAP2C and its expression has potential utility for the detection of carcinoma-in-situ in that malignancy." (PMID 24023917, 2013).
esophageal cancer (2 papers, 2020 to 2022). A primary or metastatic malignant neoplasm involving the esophagus. "For example, exosomal miR-193 silences transcription factor AP-2 gamma (TFAP2C) in the cisplatin (CDDP)-sensitive esophageal cancer cell line, thus removing CDDP's inhibition of the cell cycle and increasing chemoresistance." (PMID 35966579, 2022). "The overexpression of miR193 can promote the division and proliferation of esophageal cancer cells, and the overexpression of TFAP2C can inhibit the division and proliferation of esophageal cancer cells." (PMID 32369495, 2020).
Obesity (2 papers, 2014 to 2021). Accumulation of substantial excess body fat. "TP73, PIK3R2, SLC9A3R1, KRT5, KRT14 and TFAP2C are novel biomarkers for pathogenesis of obesity associated type 2 diabetes mellitus." (PMID 33902539, 2021).
pancreatic cancer (2 papers, 2022 to 2024). "Moreover, overexpression of CDH4, PTK6, and TFAP2C re-sensitizes pancreatic cancer cells to gemcitabine." (PMID 36289850, 2022).
Stroke (2 papers, 2021 to 2022). Sudden impairment of blood flow to a part of the brain due to occlusion or rupture of an artery to the brain. "Pharmacological components based on TFAP2C can be constructed to inhibit ferroptosis and cell death caused by excitotoxicity or endoplasmic reticulum stress and coordinate the repair of neurons after stroke." (PMID 35087573, 2021). "Pharmacological selenium administration augmented GPX4 via coordinated activation of transcription factor AP-2 gamma (TFAP2c) and special protein 1 (Sp1) to inhibit ferroptosis and exert neuroprotective effects, providing a new strategy for stroke management." (PMID 36358568, 2022).
breast tumors (1 paper, 2021). "Our data suggests that TFAP2C and PELP1 signaling plays a role in ER+ BC progression and that the PELP1 dysregulation, commonly seen in breast tumors, may contribute to enhanced TFAP2C oncogenic signaling." (PMID 33269540, 2021).
colon cancer (1 paper, 2008). "Our data identified TFAP2C and TFAP2E as potentially important new targets of transcriptional silencing in colon cancer." (PMID 18446232, 2008). "In a panel of 20 colon cancer cases, all these genes except IRX5, TFAP2E and TFAP2C showed significantly higher methylation in cancer by t-test analysis (P<0.001 for NKX2-5, DPYS SPOCK2, GALR2 and SLC16A12; P = 0.008 for FOXN4)." (PMID 18446232, 2008).
esophageal squamous cell carcinoma (1 paper, 2023). Esophageal squamous cell carcinoma (ESCC) is a type of esophageal carcinoma (EC) that can affect any part of the esophagus, but is usually located in the upper or middle third. "In addition, in esophageal squamous cell carcinoma (ESCC), TFAP2C promotes the cell cycle, where TFAP2C activates the expression of polo-like kinase 1 (PLK1) by interacting with hematological and neurological expressed 1 like (HN1L)." (PMID 37291585, 2023).
gallbladder cancer (1 paper, 2021). "TFAP2C, a transcription factor in ferroptosis, plays an important role in regulating ferroptosis sensitivity through transcription mechanisms and modulates ferroptosis in gallbladder cancer through the Nrf2 signaling pathway." (PMID 34249766, 2021).
germ cell cancers (1 paper, 2013). "Transcription factor TFAP2C has been described to be essential for primordial germ cell maintenance and to be upregulated in several human germ cell cancers." (PMID 23967156, 2013).
hemorrhagic stroke (1 paper, 2021). A stroke caused by a bleed on the brain. "Pharmacological selenium inhibits GPX4-dependent ferroptotic death, and selenome protects neurons and improves behavior following hemorrhagic stroke through regulating TFAP2c and Sp1." (PMID 35264947, 2021).
Hepatic steatosis (1 paper, 2024). Steatosis is a term used to denote lipid accumulation within hepatocytes. "Hence, we speculated that the deactivation of the TFAP2C TF upon sericin administration might suppress proliferation, reduce hepatic steatosis and subsequently alleviate liver damage." (PMID 38443583, 2024).
Hyperglycemia (1 paper, 2025). An increased concentration of glucose in the blood. "Particularly, in female PGCs, hyperglycemia leads to the aberrant retention of chromatin accessibility at pluripotency gene promoters such as Nanog and Tfap2c, inhibiting proper gene silencing and blocking the initiation of meiosis, which ultimately hinders oocyte maturation." (PMID 40921762, 2025).
lentivirus infection (1 paper, 2024). Virus diseases caused by the Lentivirus genus. "Additionally, we observed that apoptosis was not significantly induced in TFAP2C KD cells after 18 h of lentivirus infection, which aligns with the timing of EVT differentiation initiation." (PMID 38346993, 2024).
lymph node metastasis (1 paper, 2023). "However, analysis showed that lymph node metastasis may be significantly associated with high expression of TFAP2A, TFAP2C, and TFAP2E." (PMID 37859819, 2023).
osteosarcoma (1 paper, 2023). A usually aggressive malignant bone-forming mesenchymal neoplasm, predominantly affecting adolescents and young adults. "In osteosarcoma, there is a positive feedback loop between TFAP2C and Lnc00922." (PMID 37291585, 2023). "Consequently, the expression of TFAP2C is maintained in osteosarcoma to enhance malignancy and doxorubicin resistance." (PMID 37291585, 2023).
periodontitis (1 paper, 2024). An acute or chronic inflammatory process that affects the tissues that surround and support the teeth. "The results showed that the six transcriptional biomarkers were closely associated with multiple immune cells in periodontitis samples, particularly TFAP2C, CEBPG, and BNIP3." (PMID 39045324, 2024). "LURAP1L and RGS4 showed significant overexpression, whereas ALOX12B, BNIP3, CEBPG, and TFAP2C were notably underexpressed in periodontitis." (PMID 39045324, 2024). "Secondly, our study identified six transcripts that are tissue biomarkers for periodontitis (ALOX12B, BNIP3, CEBPG, LURAP1L, RGS4, and TFAP2C) potentially significant for periodontitis using three machine learning methods: LASSO, SVM, and RF." (PMID 39045324, 2024). "The study showed that TFAP2C is a master regulator of periodontitis." (PMID 39045324, 2024). "The TFAP2C and BNIP3 transcripts exhibited downregulated expression in the periodontitis group and showed significantly lower expression levels than the control subject." (PMID 39045324, 2024). "The results derived from the three machine learning methods were intersected and illustrated in a Venn diagram, revealing six transcriptional biomarkers critical for differentiating periodontitis tissues from healthy tissues: ALOX12B, BNIP3, CEBPG, LURAP1L, RGS4, and TFAP2C." (PMID 39045324, 2024).
placental insufficiency (1 paper, 2023). Failure of the placenta to deliver an adequate supply of nutrients and oxygen to the fetus. "In this mouse model, the major trophoblast differentiation regulator transcription factor AP-2y (Tfap2c) was genetically deleted, which induced a placental insufficiency and FGR at term, but without typical PE symptoms in the dam." (PMID 37108049, 2023).
placental tumor (1 paper, 2024). "For example, GATA3 and AP2 gamma (TFAP2C), two TFs that were recently reported to cooperate with TEAD4 and VGLL1 to differentiate pluripotent stem cells into trophoblast stem cells, were also identified from our ChIP-seq analysis of breast and placental tumor cells." (PMID 38912065, 2024).
sarcopenia (1 paper, 2023). Progressive decline in muscle mass due to aging which results in decreased functional capacity of muscles. "Among the four DETFs, only PAX5 exhibited significantly decreased expression, while TP73, BCL11A and TFAP2C were increased in sarcopenia." (PMID 37525094, 2023).
spina bifida (1 paper, 2024). A congenital neural tube defect in which vertebrae are not fully formed. "Moreover, conditional inactivation of Tfap2c expression in Grhl3-expressing neural plate border cells also induces spina bifida." (PMID 39296075, 2024).
squamous cell carcinoma (1 paper, 2023). A carcinoma arising from squamous epithelial cells. "The analysis of tumor differentiation shows that TFAP2A and TFAP2C are closely related to the differentiation of BLCA into basal/squamous cell carcinoma." (PMID 37859819, 2023).
steatosis (1 paper, 2018). Increased lipid within the cytoplasm of cells. "Further, targeted overexpression of TFAP2C induced the equivalent phenotype of steatosis in mouse liver, underscoring the role of TFAP2 proteins in the regulation of neutral lipid metabolism." (PMID 30256193, 2018).
teratoma (1 paper, 2013). A non-seminomatous germ cell tumor characterized by the presence of various tissues which correspond to the different germinal layers (endoderm, mesoderm, and ectoderm). "We further demonstrate that mice with a heterozygous deletion of the TFAP2C target gene Nanos3 are also prone to develop teratomas." (PMID 23967156, 2013).
testis cancer (1 paper, 2022). "To address this, we analyzed the correlation between NANOS1 and NANOS3 with its upstream transcriptional program in human primordial germ cells including transcription factors PRDM1, SOX17, TFAP2C, and PRDM14 expression in testis cancer samples." (PMID 36012673, 2022).